ADORA3 (adenosine A3 receptor)
Diseases named in the same sentence as ADORA3 in open-access papers (continued):
Sharing a sentence is not in itself a finding about the gene and the disease.
tumor (43 papers, 2003 to 2025). "The results indicated that ADORA2A (P = 0.0076) and ADORA3 (P = 0.0142) receptors were significantly upregulated in BC tissues, reported being associated with tumor immune escape." (PMID 34220957, 2021). "Despite the application of Namodenoson in clinical trials to stimulate ADORA3, the mode of action in tumor cells of this drug is only partly understood." (PMID 39911497, 2025). "ADORA3 has been described to be upregulated in tumor tissues from small groups of patients with mesothelioma, thyroid, breast and colon cancer." (PMID 39911497, 2025). "In the study of the role of ADORA3 in cancer development, as well as therapy, concentration of agonist action should be confirmed to avoid the situation of tumor-promoting proliferation because of the dual action of ADORA3." (PMID 40362672, 2025). "The reports of 2 phase II clinical trials that investigated Namodenoson in patients with MASH27 or HCC26 were based on the assumption that ADORA3 should be overexpressed in inflammatory or tumor tissues compared to healthy tissues." (PMID 39911497, 2025). "ADORA3 can have pro- or anti-inflammatory effects depending on the context and can induce apoptosis in certain tumor cells (reviewed in." (PMID 41190065, 2025). "In IGHV-unmutated cases, they reported methylation of known or potent tumor suppressor genes (for example, VHL, ABI3, and IGSF4) as well as unmethylated genes involved in cell growth and tumor progression (ADORA3 and PRF1)." (PMID 38435839, 2024). "Adenosine promotes tumor growth, can activate toll-like receptors (TLRs), and induces microglial responses via an ADORA3-dependent mechanism." (PMID 32299465, 2020). "The adenosine A3 receptor (A3R) is involved in cardiovascular, neurological and tumour-related pathologies and serves as an exceptional pharmaceutical target in the clinical setting." (PMID 25601336, 2015). "Given the observation that Namodenoson downregulates a broad range of HDAC enzymes in tumor cells, we hypothesized that a combination of ADORA3 activation and inhibition of HDACs might be able to enhance the therapeutic efficacy of either treatment alone." (PMID 39911497, 2025). "In such a scenario, the expression level of ADORA3 in tumor tissues might be an essential prerequisite for identifying patients that benefit from this approach due to our observation of quite variable ADORA3 levels in HCC- and CCA-derived patient samples." (PMID 39911497, 2025). "ADORA3 has a dual effect on the proliferation of malignant tumor cells." (PMID 40362672, 2025). "The assumption of ADORA3 overexpression in liver tumors has been based on observations in other tumors, single cases of mRNA expression in HCC tissues, or ADORA3 levels in peripheral blood mononuclear cells, which were postulated to be a surrogate marker for tumor expression." (PMID 39911497, 2025). "This led us to hypothesize that ADORA3 stimulation might induce chromatin remodeling events in tumor cells." (PMID 39911497, 2025). "Interestingly, muscle cells secrete natural agonists to ADORA3 with an antitumor effect that seems to account for the rarity of tumor metastases in striated muscles." (PMID 39911497, 2025). "On the one hand, ADORA3 expression levels on tumor cells should be analyzed before study entry." (PMID 39911497, 2025). "Additionally, analyzing RNA sequencing data from patient-derived needle biopsy samples, we compared ADORA3 expression between normal liver tissue, tumor-adjacent liver tissue, and HCC tumors." (PMID 39911497, 2025). "Moreover, several samples in both tumor types showed hardly any detectable ADORA3 staining." (PMID 39911497, 2025). "The high expression of ADORA3 in malignant tumors promotes the occurrence, development, metastasis, and other processes of tumors, such as accelerating the deterioration of tumors by promoting the proliferation of tumor cells, facilitating tumor immune escape, and promoting tumor angiogenesis." (PMID 40362672, 2025).
tumor (continued). "A detailed characterization of ADORA3 expression in HCC or CCA tumor samples has not been reported yet." (PMID 39911497, 2025). "Of note, we could not confirm higher ADORA3 levels in tumor tissues compared to normal liver tissues, neither for HCC nor CCA." (PMID 39911497, 2025). "As a result, we could confirm a similar expression pattern of ADORA3 in tumors of HCC, which was not statistically different from normal liver or tumor-adjacent tissues." (PMID 39911497, 2025).
cancer (41 papers, 2003 to 2026). A tumor composed of atypical neoplastic, often pleomorphic cells that invade other tissues. "Overexpression of ADORA3 primarily leads to the identification of DEGs that are significantly linked to neurodegenerative conditions, while gDTUs are more frequently associated with multiple pathways related to cancer." (PMID 40362672, 2025). "To characterize the influence of ADORA3 stimulating drugs on postulated antitumor effects, we next focused on antiproliferative properties in cancer cells." (PMID 39911497, 2025). "In this context, alterations in ADORA signaling pathways occur during malignant transformation, which identifies these receptors, especially ADORA3, as a potential target to treat cancer." (PMID 39911497, 2025). "Future studies should be done, utilizing technology such as siRNA or CRISPR-KO/KD, to determine the direct role of ENTPD1, NTSE, and ADORA3 in cancer cell behavior." (PMID 36186774, 2022). "Upregulated GPCRs that have been proposed as therapeutic targets in cancer included the adenosine receptors ADORA1 and ADORA3, and important GPCRs for autocrine growth factors in cancer, such as bombesin receptor NMBR, and neurotensin receptor NTSR145,46." (PMID 36220861, 2022). "The adenosine A3 receptor is a promising target for treating and diagnosing inflammation and cancer." (PMID 35408685, 2022). "The general anti-cancer mechanisms of cordycepin are regulated by the adenosine A3 receptor, epidermal growth factor receptor (EGFR), mitogen-activated protein kinases (MAPKs), and glycogen synthase kinase (GSK)-3β, leading to cell cycle arrest or apoptosis." (PMID 34443541, 2021). "Cordycepin exhibited an anti-cancer effect against B16 mouse melanoma by inducing the adenosine A3 receptor, and eventual activation of glycogen synthase kinase-3β, and the suppression of cyclin D1." (PMID 33628175, 2020). "The adenosine A3 receptor (A3R) is the only adenosine receptor subtype to be overexpressed in inflammatory and cancer cells and therefore is considered a novel and promising therapeutic target for inflammatory diseases and cancer." (PMID 32604732, 2020). "However, in recent years, research has revealed the opposite phenomenon, making ADORA3’s role in cancer complicated and contradictory." (PMID 40362672, 2025). "ADORA3 mediates multiple signaling pathways, and the specific mechanism of action of each signaling pathway affecting the proliferation, apoptosis, invasion, and metastasis of cancer cells should be clarified." (PMID 40362672, 2025). "This suggests that normal hepatocytes and cholangiocytes may respond differently to ADORA3 agonists than cancer cells." (PMID 39911497, 2025). "The adenosine A3 receptor (A3AR)is a G protein-coupledreceptor (GPCR) that exerts immunomodulatory effects in pathophysiologicalconditions such as inflammation and cancer." (PMID 37531576, 2023). "Adenosine A3 receptor (A3AR) holds promise for treating inflammatory and cancer conditions." (PMID 38627384, 2024). "Especially, the stimulation of the adenosine A3 receptor activates synthase kinase GSK-3β and suppresses cyclin D1 and then induces cell cycle arrest and DNA damage to further regulate the tumor microenvironment and target cancer stem cells." (PMID 34443541, 2021).
infection (3 papers, 2016 to 2022). The state of being infected such as from the introduction of a foreign agent such as serum, vaccine, antigenic substance or organism. "Adenosine signals via four related family A G protein-coupled receptors (GPCRs) of which the adenosine A3 receptor (A3AR) is thought to play an important role in the control of infection and related inflammation due to its expression on immune cells." (PMID 30919204, 2019).
neurodegenerative disease (2 papers, 2021 to 2025). A disorder of the central nervous system characterized by gradual and progressive loss of neural tissue and neurologic function. "When ADORA3 was overexpressed, thousands of genes were up- or downregulated; these genes were functionally enriched in a variety of functions related to RNA splicing and involved in a variety of neurodegenerative diseases, as well as oxidative phosphorylation." (PMID 40362672, 2025).
peripheral neuropathy (2 papers, 2022 to 2024). A disorder affecting the peripheral nervous system. "Adenosine A3 receptor selective agonist, MRS5890, prevented signs of cisplatin-induced peripheral neuropathy, such as mechanical allodynia, spontaneous pain, and sensorimotor deficits, highlighting the efficacy of adenosine A3 receptor agonist in neuropathic pain induced by cisplatin." (PMID 38339331, 2024).
ADORA3 also shares sentences with these, for which no sentence is quoted: rheumatoid arthritis (13 papers); colorectal cancer (4); Sepsis (4); cardiovascular disease (3); fibrosis (3); Hypertension (3); leukemia (3); liver disease (3); osteoarthritis (3); ulcerative colitis (3); atherosclerosis (2); brain infarct (2); cardiac diseases (2); chronic obstructive pulmonary disease (2); Crohn disease (2); depression (2); dry eye (2); dyslipidemia (2); inflammation (2); injury (2); subarachnoid hemorrhage (2); Acute hepatitis (1); adenoma (1); airway hyperresponsiveness (1); allergic respiratory disease (1); Allergy (1); Alzheimer disease (1); astrocytoma (1); astroglioma (1); autonomic neuropathy (1).
A further 34 diseases each share a sentence with ADORA3 in 1 paper.